BAP1 (BRCA1 associated deubiquitinase 1)
Diseases named in the same sentence as BAP1 in open-access papers (continued):
Sharing a sentence is not in itself a finding about the gene and the disease.
mesothelioma (continued). "Characteristics of mesothelioma include loss of BAP1 detected by IHC and deletion of p16 (CDKN2A) detected by FISH." (PMID 38786310, 2024). "All these observations underscore that available monotherapies for BAP1-deficient mesotheliomas are suboptimal and therefore exploring drug combinations seems prudent." (PMID 38054839, 2024). "In vivo data showed susceptibility to the combination of BAP1-deficient xenografts and demonstrated an increase of survival in autochthonous models of mesothelioma." (PMID 38054839, 2024). "Combining EZH2i with ATMi was found to have synergistic potential against BAP1-deficient mesothelioma in our drug screen, which was validated in clonogenicity assays." (PMID 38519707, 2024). "The results obtained by double agent treatment in vivo in xenografts suggests a combination effect by EZH2i/FGFRi treatment and aligns with our in vitro findings of increased sensitivity against Bap1-deficient mesothelioma tumor cells." (PMID 38054839, 2024). "For the combination, we found an overall synergy score >30 in Bap1-deficient mouse mesothelioma cell lines which is generally accepted as highly synergistic potential." (PMID 38054839, 2024). "Our extensive testing in preclinical models of BAP1-deficient mesothelioma show that inhibiting ATM in combination with EZH2 is highly synergistic, showing the potential therapeutic application of this combination." (PMID 38519707, 2024). "BAP1 is the most frequently mutated gene found in mesothelioma (pleural and peritoneal), with about 30–50% of cases harboring somatic mutations." (PMID 38642130, 2024). "In this study, we have combined the inhibition of the two previously reported vulnerabilities associated with the loss of BAP1 in patients with mesothelioma." (PMID 38054839, 2024). "Recent genome analysis with multi-sampling of the same patient’s mesothelioma tissues revealed clonality of mesothelioma cells, which showed that BAP1/3p21 loss is an early event, while NF2/22q loss is a late event." (PMID 37180489, 2023). "A recently published clinical study corroborates our findings where patients with mesothelioma with BAP1 deficiency derived limited clinical benefits from tazemetostat treatment." (PMID 36657447, 2023). "The long-term colony-formation assays and IC50 curves with ZA treatment in mouse mesothelioma cell lines show that Bap1-deficient cell lines are more sensitive to ZA treatment than the Bap1 WT cell line." (PMID 36657447, 2023). "Vinorelbine exhibits useful clinical activity in mesothelioma and BAP1 loss has been correlated with clinical efficacy in the MS01 study." (PMID 36550359, 2023). "Depletion of BAP1 protein induced proteasome-mediated degradation of BRCA1 in mesothelioma cells while loss of BAP1 correlated with BRCA1 loss in mesothelioma patient tumour samples." (PMID 36550359, 2023). "The scarcity of actionable mutations in mesothelioma limits the application of targeted drug treatments, and therefore, many trials have focussed on pathways affected by genetic alterations affecting BAP1, CDKN2A and NF2." (PMID 38015374, 2023). "Overall, our study illustrates the potential of a combination therapy targeting two key pathways in BAP1-deficient malignancies and thereby adding a new therapeutic option to the treatment landscape of mesothelioma." (PMID 36657447, 2023). "BAP1 is the most commonly inactivated gene in mesothelioma, the deficiency of which triggers cancerous transformation through disruption of DNA repair, transcription regulation, and apoptosis." (PMID 36833533, 2023). "The authors of this study, based on the presence, absence or co-occurrence of CDKN2A/B and BAP1 mutations, identified four mesothelioma subgroups with different prognostic impact." (PMID 37046732, 2023).
mesothelioma (continued). "In a forward genetic screen using a kinome CRISPR library, we identify that Bap1-deficient mesothelioma cells are sensitive to the loss of kinases belonging to a major metabolic pathway involved in mevalonate and cholesterol biosynthesis." (PMID 36657447, 2023). "Pharmacological inhibition of PRC2 elevates the expression of cholesterol biosynthesis genes only in BAP1-deficient mesothelioma, thereby sensitizing these cells to the combined targeting of PRC2 and the mevalonate pathway." (PMID 36657447, 2023). "The tumour suppressor BRCA1-associated protein 1 (BAP1) is the most frequently mutated cancer gene in mesothelioma." (PMID 36550359, 2023). "Presently it has been estimated that approximately 12% of all mesotheliomas are linked to germline mutations of BAP1 or other tumor suppressor genes; presumably in the past, these mesotheliomas were attributed exclusively to asbestos." (PMID 37880686, 2023). "Following sequencing, germline BAP1 mutations linked to autosomal dominant transmission of uveal melanoma and mesothelioma were discovered." (PMID 38136277, 2023). "A series of subsequent studies revealed inactivating mutations in BAP1 in diverse human cancers, including mesothelioma, uveal melanoma, cutaneous melanoma, and renal cell carcinoma." (PMID 36754982, 2023). "When mesotheliomas were acquired, both mutations that shortened the BAP1 gene and uncontrolled expression of BAP1 were found." (PMID 36834912, 2023). "Somatic and germline mutations of the BAP1 gene have been identified in multiple human cancers, with a particularly high frequency in mesothelioma, uveal melanoma and clear cell renal cell carcinoma." (PMID 37009801, 2023). "To confirm these results in cells of other types of cancer, we compared TG2-179-1 sensitivity between MSTO-211H and H226 mesothelioma cells, with BAP1 proficiency and deficiency, respectively." (PMID 36754982, 2023). "The gene encoding BAP1 is mutated in various human cancers, including mesothelioma, uveal melanoma and renal cell carcinoma." (PMID 36754982, 2023). "The mechanisms underlying BAP1-independent lethality due to PARP inhibition in mesothelioma cells and possibly other cancer cells remain to be elucidated." (PMID 37009801, 2023). "We observe that the majority of these genes are significantly upregulated upon BAP1 loss in human mesothelioma cells." (PMID 36657447, 2023). "We show that BAP1-deficient mesothelioma is synthetically lethal to mevalonate pathway inhibition and that it is possible to pharmacologically exploit this lethality by repurposing ZA, a drug routinely used in clinic." (PMID 36657447, 2023). "Collectively, our data show that BAP1-deficient mesothelioma cells are vulnerable to mevalonate pathway inhibition, resulting in higher sensitivity to ZA treatment." (PMID 36657447, 2023). "Overall, it is estimated that 12–16% of mesotheliomas develop in carriers of germline BAP1 mutations-the most common mutation, or of other tumor suppressor gene mutations." (PMID 37880686, 2023). "We validated the effect of BAP1 loss on several genes obtained from our analysis using inducible shRNA and synthetic gRNAs in human mesothelioma cell lines." (PMID 36657447, 2023). "There are notable differences in the clinical behaviour between sporadic mesothelioma and the form of mesothelioma associated with BAP1 TPS, with the latter having a less aggressive phenotype and patients with a higher median overall survival of 5–7 years." (PMID 38015374, 2023). "For example, CDKN2A and BAP1 germline mutations predispose melanoma and mesothelioma, while CDKN2A and HRAS were frequently mutated in vulvar squamous cell carcinoma." (PMID 37626750, 2023).
mesothelioma (continued). "The role of BAP1 mutations in mesothelioma susceptibility has been subsequently confirmed by several other reports." (PMID 37942251, 2023). "In the current study, we have used focused CRISPR-genetic screens and mouse mesothelioma cell lines with a defined genetic background for identifying targetable vulnerabilities specifically associated with Bap1 loss." (PMID 36657447, 2023). "Around 10% of mesothelioma patients are carriers of a germline mutation of BRCA1 associated protein 1 (BAP1) and have a much better prognosis." (PMID 36683050, 2023). "Mutations in BAP1 can cause various types of cancer, such as renal cell carcinoma and mesothelioma, and when BAP1 is mutated, the inhibition of SLC7A11 and the promotion of ferroptosis are lost." (PMID 36874967, 2023). "This clearly indicates that the expression pattern follows the dynamics of the H3K27me3 mark rather than H2AK119ub1, suggesting a relatively greater effect of the PRC2-mediated silencing on gene expression in Bap1-deficient mesothelioma." (PMID 36657447, 2023). "We observe that BAP1-deficient human mesothelioma cell lines (except H28) are hypersensitive to the combined treatment of EZH2 inhibitor GSK126 and mevalonate pathway inhibitor ZA." (PMID 36657447, 2023). "Tazemetostat (Zeste- Homolog 2 methyltransferase inhibitor) is a new approach to selective treatment for BAP1-mutated mesothelioma." (PMID 37469419, 2023). "The expression and chromatin analyses at genes such as USP43, HOXA6, HOXA10, and USP18 demonstrate that these genes are downregulated via PRC2-mediated silencing in BAP1-deficient mesothelioma." (PMID 36657447, 2023). "In situ mesothelioma needs to be diagnosed by immunohistochemical detection of BAP1 and/or MTAP loss, and/or by fluorescence in situ hybridization detection of CDKN2A homozygous deletion, and fully discussed with thoracic surgeons and radiologists in MDT." (PMID 37461124, 2023). "Germline BAP1 mutations cause mesothelioma and other malignancies, namely, uveal cancer, meningioma, and melanoma, overall defined as “BAP1- related cancer syndrome”." (PMID 36834912, 2023). "To explore in depth the consequences of Bap1 loss on H2AK119ub1 and H3K27me3 occupancy, we reanalyzed the chromatin profiles of BNC (Bap1-deficient) and NC (Bap1-proficient) mouse mesothelioma cells." (PMID 36657447, 2023). "There is also a positive side to carrying BAP1 mutations: mesotheliomas in these patients are for the most part less aggressive, as they are associated with a median survival of 6–7 years." (PMID 37880686, 2023). "We also have described epigenetic and expression changes that are exclusively associated with BAP1 deficiency and its potential implications in mesothelioma progression." (PMID 36657447, 2023). "Our results in BAP1-deficient mouse and human mesothelioma indicate that it is the increased PRC2 occupancy at key promoters that influences the expression status of target genes." (PMID 36657447, 2023). "Studies carried out on families with a high incidence of mesothelioma found that a germline mutation in BRCA1-associated protein 1 (BAP1) and a following somatic mutation in the same locus originate the biallelic inactivation of the gene." (PMID 37942251, 2023). "We therefore set out to characterise the consequences of BAP1 loss on mitotic progression in mesothelioma cells and discovered that BAP1 loss induces mitotic defects through both BRCA1-dependent and independent mechanisms." (PMID 36550359, 2023). "In 2011, germline mutations in BAP1 were observed in two families with a history of cancer, particularly mesothelioma." (PMID 38015374, 2023). "show that the combined targeting of mevalonate pathway and EZH2 inhibition effectively kills tumor cells and prolongs the survival of Bap1-deficient mice with mesothelioma." (PMID 36657447, 2023). "Remarkably, after BRCA1-related protein-1, NF2 is the second most often mutated gene in mesothelioma (BAP1)." (PMID 38136277, 2023).
mesothelioma (continued). "Carriers of BAP1 mutations have high frequency of mesothelioma, cutaneous and uveal melanoma, clear cell renal cell carcinoma." (PMID 36318367, 2022). "While asbestos exposure is the leading risk factor in developing mesothelioma, rare cases are genetically predisposed, such as in BAP1 mutations." (PMID 35216091, 2022). "Other causes of mesothelioma include exposure to other types of mineral fibers, radiation, chronic pleural inflammation, or germline and somatic inactivation of the BRCA1-associated protein 1 gene (BAP1)." (PMID 36439509, 2022). "This syndrome, caused by mutations in the BAP1 gene, is characterized by uveal melanoma, mesothelioma, and (less often) skin melanoma." (PMID 35465855, 2022). "Mutations in the BAP1 gene commonly result in cancers and recent findings indicate that germline BAP1 mutations cause a hereditary cancer syndrome with increased risk of mesothelioma and uveal melanoma." (PMID 34976173, 2022). "Individuals carrying familiar BAP1 monoallelic mutations display hypersusceptibility to exposure-associated cancers, such as asbestos-driven mesothelioma, thus BAP1 status has been postulated to participate in gene-environment interaction." (PMID 36318367, 2022). "MTAP loss is more common in sarcomatous mesothelioma; on the other hand, BAP-1 loss is more common in the epithelioid form of mesothelioma." (PMID 36553016, 2022). "Together with somatic mutations, a BAP1-related cancer syndrome characterized by mesothelioma, uveal melanoma, and possibly other cancer types has been identified." (PMID 35223506, 2022). "BAP1 is one of the most commonly mutated genes in PM with over 60% somatic inactivation in sporadic mesotheliomas." (PMID 36362209, 2022). "BAP1 is a high-risk locus in UM and germline BAP1 mutations increase the risk of developing UM and other tumours such as melanocytic skin tumours, mesothelioma, and renal cell carcinoma (known as the BAP1-predisposition syndrome)." (PMID 35682684, 2022). "A phase II single-arm trial evaluated the disease control rate for rucaparib in BAP1/BRCA1-deficient relapsed mesothelioma (NCT03654833)." (PMID 36362209, 2022). "Germline mutations in BRCA1-associated protein 1 (BAP1) and some DNA repair genes have been considered as predisposing genetic factors associated with mesothelioma development." (PMID 36362413, 2022). "In contrast, somatic BAP1 mutations are frequent in various human cancers, including uveal melanoma and mesothelioma, and have been noted in breast, lung, and renal cancers." (PMID 34976173, 2022). "BAP1 cancer syndrome was first identified as a distinct cancer predisposition in families in which mesothelioma and uveal melanoma co-segregated with BAP1 germline pathogenic variants." (PMID 35381901, 2022). "BRCA-1-associated protein (BAP1) is a tumor suppressor gene which shows biallelic inactivation in approximately half of all mesotheliomas." (PMID 36380343, 2022). "The reason for this choice is that nuclear BAP1, as routinely assessed in the clinic, has been recently demonstrated to be associated with clinical outcome in chemotherapy treated mesothelioma patients." (PMID 36221913, 2022). "Unlike in ATs, the BAP1 tumor suppressor gene mutation has been defined as a frequent genetic alteration in mesotheliomas, and an associated loss of nuclear BAP1 immunostaining has been shown to be present in more than 80% of multiple case series." (PMID 36572896, 2022). "The carriers of BAP1 gene mutations are also prone to developing clear cell renal cell carcinoma or mesothelioma." (PMID 35465855, 2022). "There is evidence that mesothelioma is less aggressive when it arises in the setting of BAP1 cancer syndrome, whereas the effect of somatic BAP1 variants on mesothelioma prognosis is minimal." (PMID 35381901, 2022). "This HAND2-expressing group of mesothelioma tumors did not cluster notably with tumors featuring differential expression of the common mesothelioma-associated tumor suppressor genes BAP1 and CDKN2A." (PMID 35354817, 2022).
mesothelioma (continued). "Inactivating mutations or truncation of Bap1 frequently occur in familial cancers such as uveal melanoma, mesothelioma, cutaneous melanoma, and renal cell carcinoma." (PMID 35052618, 2022). "The destabilization of dsRNA structures upon ADAR activity suppresses the cellular response to dsRNA by preventing type‐1 IFN signaling, and the TCGA study has revealed that in mesothelioma this activation occurs in tumors with mutated BAP1." (PMID 36221913, 2022). "Around 12% of patients presenting with asbestos-unrelated mesotheliomas carries germline mutations in BRCA1-associated protein 1 (BAP1) or other tumor suppressor genes." (PMID 36471440, 2022). "For instance, BAP1 gene mutations have been reported in 23 to 64% of mesotheliomas resulting in nuclear loss of expression of BAP1 protein." (PMID 35565429, 2022). "Family A was one of the first families to be tested for BAP1 mutations in 2015 due to a known familial history of mesothelioma." (PMID 35885614, 2022). "Here, we discuss the current knowledge about the contribution of inactivating BAP1 mutations in development and progression of inherited cancers as Mesothelioma, Uveal melanoma and Clear Cell Renal Cell Carcinoma in which BAP1 is recurrently lost." (PMID 36318367, 2022). "Their work has shown how mesotheliomas mostly follow a linear evolution with BAP1 being the most frequent ancestral mutation and NF2 arising mainly as a late event." (PMID 35204459, 2022). "Recently, the interest in the role of BAP-1 (BRCA1-associated protein–1) in mesothelioma has increased." (PMID 36553016, 2022). "One biliary ITPN carried a STOP mutation of BAP1, a gene that was previously suggested as a candidate for a predictive biomarker for immunotherapy of mesothelioma." (PMID 34205964, 2021). "BAP1 is mutated or deleted in many cancer types, including mesothelioma, uveal melanoma, and cholangiocarcinoma." (PMID 34186021, 2021). "Loss of BAP1 expression has been demonstrated in many other tumors including melanoma, mesothelioma and RCC." (PMID 34830985, 2021). "A larger series documented several families presenting with melanoma and mesothelioma secondary to an inherited BAP1 (p.Asp404*) germline truncating mutation, and one case of papillary meningioma was identified by autopsy." (PMID 34504799, 2021). "High frequency of germline mutations of BAP1 were demonstrated to cause mesothelioma in 2001, when an epidemic spread of cases was reported in a village in Cappadocia." (PMID 34249695, 2021). "Today, the assessment of BAP1 status has become part of the diagnostic routine of mesothelioma allowing to distinguish between benign and malignant mesothelial cells and to identify biphasic mesothelioma." (PMID 34249695, 2021). "A functional genomic screen in mesothelioma uncovered that loss of function of BRCA1-associated protein 1 (BAP1) is associated with vulnerability to ribonucleotide reductase (RNR) inhibitors such as gemcitabine." (PMID 34572827, 2021). "It has been recently reported that mesothelioma cells that lack BAP1 (BRCA1 Associated Protein) are sensitive to inhibition of the EZH2 (Enhancer of Zeste Homolog 2) histone methyltransferase." (PMID 34277422, 2021). "Following BAP1, the second most frequent mutated gene in mesothelioma is the neurofibromatosis type 2 (NF2) which encodes the protein merlin." (PMID 34249695, 2021). "BAP1 mutations are known to cause various types of cancers, including mesothelioma, and are referred to as “BAP1 tumor predisposition syndrome”." (PMID 34641979, 2021). "Among the somatic mutations occurring during tumor cell proliferation, BAP1 mutations have been observed in approximately 60% of mesotheliomas." (PMID 34641979, 2021). "Somatic mutation of the BAP1 gene in mesothelioma was first described in 2011, with mutations occurring in approximately 70% of epithelioid mesotheliomas." (PMID 34209209, 2021).